PCNA (proliferating cell nuclear antigen)
Diseases named in the same sentence as PCNA in open-access papers (continued):
Sharing a sentence is not in itself a finding about the gene and the disease.
cancer (continued). "APOBEC1 complementation factor, an oncogene in many cancers, is highly expressed and closely related to the prognosis and progression of EC by downregulating the expression of PCNA." (PMID 34721621, 2021). "We simultaneously analyzed the expression of the cancer biomarkers PCNA, Ki-67, and pH3 in the same tissue samples." (PMID 34071030, 2021). "We demonstrate that promoter activity of the PCNA promoter is high and the same in cancer cells and fibroblasts." (PMID 33804861, 2021). "The use of other proliferation-associated proteins, such as proliferating cell nuclear antigen (PCNA) and mini chromosome maintenance proteins (MCM), as cancer proliferation biomarkers has been also suggested." (PMID 34073937, 2021). "As PCNA is an important protein for cancer cell growth and survival, PCNA represents a potential target for anticancer therapy." (PMID 33498235, 2021). "PCNA, Ki-67, and pH3 are well accepted cancer biomarkers, thus, we decided to compare IRS-4 expression pattern with those of the three proteins using immunohistochemistry methods." (PMID 34071030, 2021). "For cisplatin-DNA lesions, the polymerase η with the assistance of monoubiquitinated proliferating cell nuclear antigen (PCNA) has emerged as the main TLS polymerase that allows cancers to develop resistance to this type of chemotherapy." (PMID 33396303, 2020). "It has also to be mentioned the PCNA pivotal role in cancer, owing to its function in cell proliferation." (PMID 33218180, 2020). "In situ proximity ligation assay identified frequent IGF1R and PCNA colocalization in many cancer types." (PMID 32701997, 2020). "Identification of inhibitors of this pathway holds promise in cancer therapy since PCNA ubiquitination plays a central role in DNA damage tolerance and resulting mutagenesis." (PMID 32228444, 2020). "MMP-2 activity and the expression of PCNA, Ki-67 and CD31 which are associated with cancer growth, invasion, and migration, increased after CIH treatment." (PMID 32024881, 2020). "Mechanistically, we observed more cytoplasmic PCNA in neutrophils treated with the supernatant of cancer cell lines than SF media." (PMID 33049964, 2020). "IGF1R kinase inhibition abolished PCNA/RAD18 interaction and PCNA-mono-ubiquitination showing that this mechanism extends to cancer cells." (PMID 32701997, 2020). "The results showed that the expression of HNRNPA2B1 was significantly positively correlated with the expressions of MKI67 and PCNA, which were the classic biomarkers of proliferative cancer cells." (PMID 33134163, 2020). "This high purity BTFS inhibited the proliferation of A2780/CP70 cancer cells dose-dependently, which is evidenced by the inhibition of cell viability, reduction of colony formation ability, and suppression of PCNA protein expression." (PMID 32752095, 2020). "In healthy cells, PCNA appears to be expressed in the nucleus and is involved in DNA replication and repair, whereas in cancer cells, it is overexpressed on the cell surface." (PMID 32153582, 2020). "Across different types of cancer tissues, we observed that nuclear IGF1R was colocalized with PCNA, indicating that a significant proportion of human cancers depend on this mechanism for DNA damage tolerance." (PMID 32701997, 2020). "Cell growth is a necessity for the progression of cancer at primary and metastatic sites, and PCNA is a crucial factor for DNA replication; thus, the inhibition of PCNA is considered to be a viable anticancer strategy." (PMID 32566099, 2020). "A number of parameters, such as PCNA expression, establish that growth of cancer, once seeded in fatty liver, is enhanced." (PMID 32879136, 2020). "In this study we aimed to explore and describe the potential interaction between IGF1R and PCNA in cancer tissue and cancer cell lines." (PMID 32701997, 2020).
cancer (continued). "T2AA (T2 amino alcohol), for instance, is a small molecule inhibitor that sensitizes cancer cells to cisplatin by binding to PCNA and interfering with TLS, resulting in DSB formation and the inability to replicate past inter-strand crosslinks (ICLs)." (PMID 33023096, 2020). "Cell proliferation and apoptosis have been reported to be key processes of cancer development, characterized by potential targets of proliferation-related protein PCNA, antiapoptotic protein Bcl-2, and proapoptotic protein Bax." (PMID 32051829, 2020). "NKp44 recognizes the proliferating cell nuclear antigen (PCNA) that is over-expressed in cancer cells." (PMID 32054102, 2020). "PCNA is a marker capable of informing the diagnosis and prognosis of various cancers due to its high expression in proliferating cells." (PMID 33158043, 2020). "Proliferation markers, such as proliferating cell nuclear antigen (PCNA), Ki-67, and thymidine kinase 1 (TK1), have potential as diagnostic tools and as prognostic factors in assessing cancer treatment and disease progression." (PMID 33292474, 2020). "Adjustment of DNA repair gene expression by the PCNA metagene has enabled us to view cancer from a distant perspective based on high-granularity involvement of DNA repair pathways in cancer." (PMID 30965671, 2019). "ERG also modulates the expression of FOS and PCNA, which are focus molecules in Network IV that includes DNA replication, recombination, and repair, cancer, Organismal injury and abnormalities." (PMID 31303963, 2019). "It was further confirmed that a large number of vessels were found to be PCNA+ in 4T1 cancers (53.4%), indicating that endothelial cells (ECs) were proliferative." (PMID 31164151, 2019). "Studies have shown that histone deacetylase 4 (HDAC4) and proliferating cell nuclear antigen (PCNA) are highly expressed in cancers." (PMID 31552187, 2019). "Approximately 50% of the genome is co-regulated by PCNA, and because its effect is so widespread, it is imperative that investigations in cancer research account for and remove the effects of this non-cancer related transcriptional mechanism." (PMID 30759820, 2019). "The similar inhibitory expression patterns of cancer progression proliferation marker PCNA in CD133+ cells indicate that IL-32γ can suppress the carcinogenic properties of CSCs as compared with control." (PMID 31263095, 2019). "There was also an inverse relationship between miR-497-5p expression and PCNA expression, which was always highly expressed in cancer tissues." (PMID 31409724, 2019). "In particular, genes like MYC, MKI67, CTNNB1, PCNA, NKX3.1, ACPP and kallikreins are warranted further investigation as diagnostic markers for cancer and cell proliferation." (PMID 31519932, 2019). "In a previous work we have observed a similar nuclear swelling and rise of pan-γ-H2AX pattern in cancer cells transduced with anti-PCNA or anti-DNA polymerase alpha inhibitory Fabs." (PMID 30871194, 2019). "RNA expression of TOP2A, PCNA, SOX2, EZH2, ZEB1 genes associated with cell cycle, cancer cell ‘stemness’, and FOXM1‐FOXO activities was similarly affected in both cases." (PMID 30927552, 2019). "For the simultaneous adjustment of expression for age, stage, and PCNA metagene (first A,S,P column), all of the 12 cancers resulted in PCs whose KM test result were significant." (PMID 30965671, 2019). "Shimoni also investigated PCNA adjustment of RNA-Seq expression during survival analysis for 34 cancers from TCGA and reported that PCNA adjustment removed statistical significance for OS prediction and resulted in random bias." (PMID 30965671, 2019). "In this study, we show for the first time that targeting PCNA can increase the anti-cancer efficacy of targeted therapies." (PMID 31921382, 2019). "PCNA is known to be highly up regulated in HPV positive cancers and is known to play a major role in cancer neoplasia." (PMID 31143704, 2019).
cancer (continued). "DC-CIK significantly enhanced the apoptosis ratio, depending on DC-CIK cell numbers, by increasing caspase-3 protein expression and reducing proliferating cell nuclear antigen protein expression against cancer stem cell." (PMID 30944835, 2019). "This study demonstrates for the first time that the PCNA-targeting peptide ATX-101 increases the anti-cancer effects of the EGFR/HER2/VEGFR inhibitor AEE788." (PMID 31921382, 2019). "There are pre-clinical molecules known to target and kill cancer cells harboring this unique form of PCNA and thus represent a potential prevention agent that stops recently immortalized cells in their tracks." (PMID 31555644, 2019). "Based on the effect on the expression of the proliferation marker PCNA, we found that the proliferation of the cancer cells was also significantly inhibited upon C278 treatment as indicated by the decreased expression of the PCNA." (PMID 31357586, 2019). "PCNA is overexpressed in many cancer types, and PCNA overexpression is correlated with cancer virulence." (PMID 29875773, 2018). "It is clear that fundamental research into the structure and binding of therapeutic drugs to PCNA and β-clamp has led to promising advancements in the areas of infectious disease and cancer." (PMID 30406112, 2018). "Proliferation is a key property of cancers, which is widely estimated by the assessment of factors like PCNA or Ki-67." (PMID 29471858, 2018). "The scaffold role of PCNA in DNA replication is essential for normal cellular proliferation, uncontrolled proliferation being one of the hallmarks of cancer." (PMID 30126151, 2018). "Altogether, clinical application of peptides or small molecules against PCNA should take this concern into account and try to achieve a more specific drug delivery to target cancer cells." (PMID 29875773, 2018). "NKp44 recognizes proliferating cell nuclear antigen (PCNA) expressed on the membrane of cancer cells." (PMID 29875773, 2018). "Consistent with the in vitro studies, the IHC results showed that the proliferation of cancer cells was inhibited in the BxPC-3-shYAP group, as there was less and weaker expression of PCNA in the BxPC-3-shYAP group compared with the BxPC-3-shNC group." (PMID 29587800, 2018). "These inhibitors that are targeted to PCNA involved in DNA repair can sensitize cancer cells to existing anti-cancer therapeutics, and a DNA aptamer has also been shown to inhibit PCNA." (PMID 30406112, 2018). "PCNA staining was significantly reduced in co-treated tumors, suggesting a reduction of cancer cell proliferation." (PMID 29789630, 2018). "Ki67 and PCNA (proliferating cell nuclear antigen) are widely used in routine cancer investigation as proliferation promoters." (PMID 29495605, 2018). "Ki-67 is a proliferating cell nuclear antigen expressed by several proliferating cancer cells and is generally used to distinguish rapidly proliferating cancerous cells from normal cells." (PMID 29304038, 2018). "This is different from the activity of two small molecule PCNA inhibitors of cancer cell growth that disrupt PCNA during replication, T2AA and PCNA-I1, and rely on the high proliferation rate of these cells." (PMID 30406112, 2018). "Ultimately, more data needs to be collected to elucidate the function of cytoplasmic PCNA and cancer migration and invasion to provide new insights into the pathological improvement of cancer." (PMID 29642589, 2018). "Utilizing agents against PCNA raise a concern as PCNA is a hub protein that takes part in many cellular interactions also in non-cancer proliferating cells." (PMID 29875773, 2018). "To rule out this possibility, we normalized the expression value of CEP55 with key proliferation markers, KI67 and PCNA using the TCGA (The Cancer Genome Atlas) dataset (n = 492)." (PMID 30108112, 2018).
cancer (continued). "In this study we demonstrate an increased anti-cancer efficacy of cisplatin when combined with the PCNA-targeting APIM-peptide, both in vitro in human BC cell lines and in vivo in the MIBC model." (PMID 30197755, 2018). "Given PCNA’s role as a scaffold protein affecting multiple signaling pathways involved in regulation of metabolism, apoptosis, DNA repair and cell cycle, and its overexpression in several cancers, PCNA has emerged as a potential target in cancer therapy." (PMID 29545934, 2018). "NKp44-pep8 interaction with PCNA, strength the evidence of PCNA role in regulation of the extracellular immune response as NKp44-pep8 target PCNA in a functional domain, which lead to cancer cell death." (PMID 29875773, 2018). "A previous study has shown that a pol β polymorphic variant, polβR137Q is associated with cancer due to its impaired polymerase activity and its deficiency in interacting with a BER cofactor, proliferating cell nuclear antigen (PCNA)." (PMID 28475635, 2017). "UHRF1 levels have been well correlated with Ki67 and PCNA which are widely used proliferation markers in cancers." (PMID 28881702, 2017). "The proliferation of cancer cells was significantly lower in the fat invasion model, as shown by luciferase assays (p<0.05) and PCNA immunohistochemistry (p<0.05)." (PMID 28407685, 2017). "As a result, we confirmed DNA polymerization complex genes, such as MCM2, PCNA, and cell cycle related genes, that were depleted by metformin treatment in RNA and protein level in 5-Fu resistant cancer cell line." (PMID 28915611, 2017). "Both the inhibition/degradation of USP1 and the increase in mono-ubiquitinated PCNA are new activities for PEITC that can explain the previously recognized ability of ITCs to enhance cancer cell sensitivity to cisplatin treatment." (PMID 28881649, 2017). "It has been suggested that PCNA plays an important role in cancer owing to its function in cell proliferation including in ovarian cancer." (PMID 28722704, 2017). "The data agree well with previous studies indicating that the observed higher concentration of PCNA protein is related to cancer progression, although the number of samples used in this study is rather small." (PMID 28722704, 2017). "Cell proliferation was significantly decreased in Terc null, TRF2 null, and K14Cre;TRF2f/f;Terc-/- cancers compared to control SCC as determined by PCNA immunohistochemistry (9%, 5%, and 20% vs. 45%; P < 0.001)." (PMID 29113290, 2017). "After 48 and 72 hours, cancer cells showed again elevated PCNA gene expression (41°C: FD 2.5 and FD 4.3, 43°C: FD 2.5 and FD 4.1, respectively)." (PMID 29403306, 2017). "Mechanistically, we found CCEPR upregulates the expression of PCNA in mRNA and protein level to promote cancer growth." (PMID 28574830, 2017). "By contrast, prostate sections from patients with evanescent carcinoma had less PCNA+CD20+ B cells and contained well-organized FDC networks." (PMID 28567040, 2017). "Thereby, data depicts that Bet-CA restricts cancer cell proliferation and to ensure this phenomenon, we strategically quantified the levels of PCNA expression and BrdU incorporation in tumors." (PMID 27003027, 2016). "Iso-3 induced growth arrest of cancer cells in G0/G1 concomitant with increased p21 and p27 expression and reduced cyclin E1, PCNA and c-myc levels." (PMID 27006469, 2016). "As with cancer cells, trophoblasts also exhibit high proliferation rates with high levels of PCNA protein." (PMID 27765926, 2016). "Our immunohistochemical staining of liver tissues showed significant increase of Ki67, PCNA and EGFR expression in DEN-treated mice; treatment with sgp130 markedly decreased the staining of these cancer-associated biomarkers." (PMID 27080032, 2016). "Surprisingly, PCNA expression was found to inhibit NK cell function upon engagement with NKp44, potentially promoting cancer escape from immune detection." (PMID 27102296, 2016).
cancer (continued). "Nuclear PCNA has a well-documented role in cancer and through its ability to control the replication fork is central in determining both tumor progression as well as anticancer treatment outcomes." (PMID 27759041, 2016). "We and others had previously shown that PCNA expression can be utilized by cancer cells to suppress NK cell activity, through interaction with the NK receptor NCR2/NKp44." (PMID 27102296, 2016). "Antigen Ki67 and proliferating cell nuclear antigen (PCNA) are nuclear proteins that are associated with and necessary for cell proliferation, and are established biomarkers for cancer diagnosis." (PMID 27080032, 2016). "The correlation between LARP1 and PCNA in cancer cell proliferation was determined using the Spearman’s correlation coefficient test." (PMID 27614686, 2016). "As a corollary, nuclear PCNA has been proposed as a potential target for inhibiting cell proliferation in cancer." (PMID 27759041, 2016). "For this reason, PCNA is regarded as an index to assess state of cell proliferation and is always used to judge the malignant degree and prognosis of cancer." (PMID 26495015, 2015). "Consist with in vitro studies, the immunohistochemistry results showed that the proliferation of cancer cells was inhibited by GA administration as there was less and weak expression for PCNA in GA group compared with that in Control group." (PMID 25895130, 2015). "Immunohistochemical of PCNA staining of the colon sections from the cancer group revealed higher number of positive cells than those from the AOM treated groups." (PMID 26201720, 2015). "Our results revealed that the CdCl2(C14H21N3O2) complex exhibited inhibitory effects against ACF productions via the suppression of PCNA expression when compared with the cancer control group." (PMID 26201720, 2015). "If cancer cells proliferate actively, especially cells in S phase characterized with DNA synthesis, the expression of PCNA will increase significantly." (PMID 26495015, 2015). "The proliferative activity of cancer cells was determined by immunohistochemical staining of the proliferating cell nuclear antigen Ki67." (PMID 25473902, 2015). "The PCNA-positive cells (%) of the colon tissue in the cancer control group were 100%, whereas PCNA-positive cells (%) from the treated group were 47.4% and 35.4%, respectively (p < 0.05)." (PMID 26201720, 2015). "Beta-sitosterol scavenges free radicals and has shown potential as an anti-cancer drug through changed expression of beta-catenin and proliferating cell nuclear antigen (PCNA)." (PMID 25690418, 2015). "This study led to the identification of SAR-24, a compound with superior potencies and potentially improved solubility, which will be used for future development of PCNA-targeting cancer therapies." (PMID 25729582, 2015). "IHC staining showed that PanIN lesions/carcinoma were labeled positively for PCNA in p48Cre/+-LSL-KrasG12D/+ mice fed AIN-76A diet alone." (PMID 26429877, 2015). "Ubiquitinated PCNA mediates error-prone DNA synthesis, which has been postulated as a primary factor for genomic instability and cancer development, although, the direct evidence is minimal." (PMID 24765138, 2014). "Several attempts have been made in recent years to block various aspects of PCNA function with promising results, demonstrating the potential of PCNA as a target for anti-cancer therapies." (PMID 24728180, 2014). "There is currently a considerable interest in the development of PCNA inhibitors as broad spectrum anti-cancer agents, because of the indispensible role of PCNA in regulating DNA replication and most DNA repair pathways." (PMID 24728180, 2014). "Of the 102 cases stained for PCNA+ TAMs, residual cancer burden (RCB) data following neoadjuvant chemotherapy and surgical excision was available for 90 cases." (PMID 24205370, 2013).